NR2F6 (nuclear receptor subfamily 2 group F member 6)
Diseases named in the same sentence as NR2F6 in open-access papers (continued):
Sharing a sentence is not in itself a finding about the gene and the disease.
cervical cancer (continued). "Western blot and real-time PCR were performed on 10 paired cervical carcinoma tissues and the adjacent noncancerous tissues to determine NR2F6 expression in the cervical cancer tissues." (PMID 27775588, 2016). "However, further studies are needed to verify our results in a larger cervical cancer cohort with LNM and to investigate the mechanism of NR2F6 promotion of LNM in cervical cancer." (PMID 27775588, 2016). "NR2F6 mRNA and protein expression were upregulated in all cervical cancer samples compared to the matched adjacent noncancerous samples." (PMID 27775588, 2016). "Lastly, we found that high NR2F6 protein expression was significantly correlated with shorter OS in the LNM-free subgroup, which suggests that NR2F6 might be a potential predictive biomarker of poor OS in patients with cervical cancer without LNM." (PMID 27775588, 2016).
lung carcinoma (8 papers, 2018 to 2024). "High expression of NR2F6 in lung cancer was also significantly associated with poor prognosis." (PMID 36119482, 2022). "NR2F6 expression reportedly regulates proliferation; in particular, NR2F6 knockdown significantly inhibits lung cancer cells via miR-142-3p." (PMID 38132359, 2023). "Next, the relationship between NR2F6 expression and the clinicopathological features of lung cancer was analyzed via immunohistochemistry, and the relationship between NR2F6 expression and prognosis was analyzed using the Kaplan–Meier Plotter." (PMID 36119482, 2022). "Relationship between expression of NR2F6 in lung cancer tissues and clinicopathological features of lung cancer." (PMID 36119482, 2022). "The TCGA database and immunohistochemical results showed that HNRNPD was highly expressed in lung cancer tissues and was highly consistent with NR2F6 expression in these tissues." (PMID 36119482, 2022). "The influence of NR2F6 knockdown on the proliferation capacity of lung cancer cells was then verified at cell level." (PMID 36119482, 2022). "The study also found that HNRNPD was highly expressed in lung cancer tissues and that its high expression level was highly consistent with the expression distribution of NR2F6." (PMID 36119482, 2022). "The protein and mRNA levels of NR2F6 in lung cancer cell lines A549, H1650, PC-9, H460, H1975, and H358 were significantly higher than those in Beas-2B." (PMID 36119482, 2022). "The impact of HNRNPD knockdown on the proliferation capacity of lung cancer cells was verified at cell level, and the relationship between NR2F6 and HNRNPD was verified by co-immunoprecipitation." (PMID 36119482, 2022). "In order to study the roles of HNRNPD and NR2F6 and their correlation in lung cancer, the TCGA database and immunohistochemical analysis were further used for verification." (PMID 36119482, 2022). "The cell experiments in the present study demonstrated that the knockdown of NR2F6 can inhibit the proliferation of lung cancer cells." (PMID 36119482, 2022). "The protein and mRNA levels of NR2F6 in normal lung epithelial cell line Beas-2B and six lung cancer cell lines were further detected." (PMID 36119482, 2022). "At cell level, NR2F6 knockdown was found to inhibit the proliferation of H460 and H358 in lung cancer cells." (PMID 36119482, 2022). "When using a staining score from 0 to 4, lung cancer tissue clearly contained higher numbers of NR2F6-expressing TILs when compared to healthy lung tissue." (PMID 29670099, 2018). "Analyzing mouse tumor models in vivo, human T cells ex vivo, and human lung cancer samples, we provide direct evidence that NR2F6 acts as an immune checkpoint." (PMID 29670099, 2018). "The study found that NR2F6 was highly expressed in lung cancer and that the knockdown of NR2F6 could inhibit the proliferation of lung cancer cells." (PMID 36119482, 2022). "Furthermore, it was found that the knockdown of HNRNPD can inhibit the proliferation of H460 lung cancer cells, and the interaction between NR2F6 and HNRNPD-coded proteins was confirmed by IP." (PMID 36119482, 2022). "As the results showed that the knockdown of NR2F6 could inhibit the proliferation of lung cancer cells, the effect of the knockdown of HNRNPD on the proliferation of lung cancer cells was further investigated." (PMID 36119482, 2022). "NR2F6 may interact with HNRNPD to jointly regulate the progression of lung cancer, and this conclusion provides a new experimental basis for the study of the molecular targeted therapy of NSCLC." (PMID 36119482, 2022). "Furthermore, the TCGA database and immunohistochemical results showed that HNRNPD was highly expressed in lung cancer tissues and was highly consistent with NR2F6 expression in these tissues." (PMID 36119482, 2022).
lung carcinoma (continued). "In order to further investigate the molecular mechanism of NR2F6 in lung cancer, an immunoprecipitation test was conducted on flag proteins in H460 cells transfected with Flag-NR2F6 lentivirus, after which the protein bound to Flag-NR2F6 was detected using mass spectrometry." (PMID 36119482, 2022). "In addition, the Western blotting and qPCR results showed that the protein expression and mRNA level of NR2F6 in lung cancer tissues were significantly higher than those in para-carcinoma tissues." (PMID 36119482, 2022). "First, the expression of NR2F6 in lung cancer tissues was analyzed using the Gene Expression Omnibus and the Cancer Genome Atlas (TCGA) databases, and the expression of NR2F6 in lung cancer tissues and cells was verified by Western blotting and quantitative polymerase chain reaction." (PMID 36119482, 2022). "A high expression of NR2F6 in lung cancer tissues was verified in the TCGA database." (PMID 36119482, 2022). "The mass spectrometry analysis results revealed that 28 proteins interacted with NR2F6, from which the key protein that could promote the progression of lung cancer—HNRNPD—was screened out." (PMID 36119482, 2022). "NR2F6 was highly expressed in lung cancer tissues and cells, and its expression was positively correlated with the depth of invasion, lymphatic metastasis, and clinical stage of lung cancer." (PMID 36119482, 2022). "Therefore, adenocarcinoma H358 and large cell carcinoma H460 with the highest expression levels of NR2F6 were selected as the stable lung cancer cell lines for the subsequent construction of the knockdown model of NR2F6." (PMID 36119482, 2022). "Notably, in the tumor-infiltrating T cells of 54% of lung cancer patients, NR2F6 upregulation has been observed within the TME." (PMID 29670099, 2018). "Specifically, CAR-T cells combined with NR2F6 gene modification might thus represent an opportunity to extend the clinical efficacy of CAR-T cell immunotherapy to the treatment of advanced/metastatic NSCLC lung cancer in the future." (PMID 34073258, 2021). "In primary lung cancer, NR2F1 and NR2F2 influence the migration and invasion of tumor cells, while NR2F6 acts as an immune checkpoint factor to modulate immune processes." (PMID 39311119, 2024). "In contrast, FKBP10 expression was significantly correlated with NR2F6 expression in specimens from patients with melanoma, pancreatic, and lung cancer, suggesting the requirement of TME components for the NR2F6 control of tumor-intrinsic FKBP10 expression." (PMID 37406115, 2023). "The generation of specific lung cancer animal models for NR2F1, NR2F2, and NR2F6 will not only enhance the understanding of the molecular mechanisms of lung cancer but also improve the diagnosis and therapy for lung cancer associated with NR2F family dysregulation." (PMID 39311119, 2024). "Currently, there are no reports on whether NR2F6 is related to the progression of lung cancer, although previous studies have shown that it may play a role in actively regulating the survival rate of tumor cells and inducing cancer progression." (PMID 36119482, 2022). "In lung cancer, it was shown that NR2F6 was expressed in lymphocytes and not in cancer cells." (PMID 32752295, 2020).
melanoma (8 papers, 2018 to 2025). A malignant, usually aggressive tumor composed of atypical, neoplastic melanocytes. "Correspondingly, higher NR2F6 expression in melanoma patient specimens was associated with a less favorable prognosis and a poor response to ICT." (PMID 37406115, 2023). "NR2F6 was selected from 48 candidate NRs based on an expression pattern in melanoma patient specimens (i.e., IFN-γ signature) associated with positive responses to immunotherapy and favorable patient outcomes." (PMID 37406115, 2023). "In a mouse melanoma model, the loss of NR2F6 enhanced the response to anti‐PD‐1 ICB." (PMID 39169517, 2024). "Towards this, we used ANSIA to measure the effect of NR2F6 gene silencing on human dermal fibroblasts resistance to invasion of A375, a cell line derived from malignant melanoma." (PMID 40847025, 2025). "NR2F6 is previously known as an orphan nuclear receptor involved in anti-tumor immunity, and genetic ablation of NR2F6 in melanoma conferred a more effective response to PD-1 therapy." (PMID 38829910, 2024). "By contrast, NR2F6 depletion both in tumors and systemically promoted a further decrease in melanoma growth by 86.37 to 91.69%." (PMID 37406115, 2023). "Correspondingly, genetic ablation of NR2F6 in a mouse melanoma model conferred a more effective response to PD-1 therapy." (PMID 37406115, 2023). "NR2F6 loss in B16F10 and YUMM1.7 melanoma cells attenuated tumor development in immune-competent but not -incompetent mice via the increased abundance of effector and progenitor-exhausted CD8+ T cells." (PMID 37406115, 2023). "Here, we report that combined ablation of NR2F6 both globally and in the injected melanoma cells synergistically antagonized tumor growth in mice, suggesting that distinct albeit complementing activities enhance antitumor immunity." (PMID 37406115, 2023). "Inoculation of NR2F6 KO mice with NR2F6 KD melanoma cells further decreased tumor growth compared with NR2F6 WT mice." (PMID 37406115, 2023). "S2E), while NR2F6 KD notably delayed melanoma growth in mice treated with anti–PD-1 antibodies, suggesting that NR2F6 loss converts B16F10 cells from an immunologically cold to warm status to allow a response to ICT." (PMID 37406115, 2023). "Given the correlation in melanoma specimens, we set to correlate NR2F6, NACC1, and FKBP10 expression with patients’ overall survival and response to ICT in other cancer types." (PMID 37406115, 2023). "Here, we identify a previously undisclosed role for the orphan nuclear receptor NR2F6 in tumor-intrinsic control of immune evasion by melanoma cells, a function highly relevant to ICT effectiveness." (PMID 37406115, 2023). "To evaluate the contribution of CD4+ and CD8+ T cells to the observed decreased tumor outgrowth, we challenged Nr2f6−/− subcutaneously with 1×105 B16-OVA melanoma cells and treated them with CD4+ and CD8+ depleting antibodies." (PMID 29670099, 2018). "Of importance, Nr2f6-deficient mice are protected against MHC-I negative B16-F10 melanoma lung metastasis formation, especially with IL-15 complex treatment, indicating the potential of NR2F6 to affect NKp46-dependent NK cell-mediated tumor surveillance." (PMID 39920136, 2025). "Furthermore, the inoculation of NR2F6 knockout mice with NR2F6 knockdown melanoma cells resulted in a further decrease in tumour progression compared with NR2F6 wild‐type mice." (PMID 39169517, 2024). "Here, we show that tumor-intrinsic NR2F6 expression in melanoma cells may mediate immune evasion by controlling the expression of genes that suppress antitumor immunity." (PMID 37406115, 2023). "Likewise, NR2F6 expression was unchanged in cultured human melanoma cells before and after IFN-γ or tumor necrosis factor–α (TNFα) treatment [fig." (PMID 37406115, 2023). "NR2F6 activity in melanoma impacts its response to anti-tumor immunity." (PMID 37406115, 2023).
melanoma (continued). "Important corroboration of our findings, tumor-intrinsic NR2F6, came from independent scRNA-seq analysis of human melanoma specimens: NR2F6, NACC1, and FKBP10 expression in malignant melanoma cells was significantly higher in samples from patients that are nonresponsive to anti–PD-1–based ICT." (PMID 37406115, 2023). "S5, M and N), suggesting that NACC1 regulation by NR2F6 is conserved in mouse and human melanoma." (PMID 37406115, 2023). "Unlike NACC1, FKBP10 expression was not affected by NR2F6 loss in human melanoma cells." (PMID 37406115, 2023). "The knockout of NR2F6 in both B16F10 and YUMM1.7 melanoma cells resulted in a reduction in tumour growth in immune‐competent mice, but not in those lacking immune competence." (PMID 39169517, 2024). "NR2F6 expression in tumor cells was inversely correlated with that of IFN-γ signature genes and with overall melanoma patient survival, observations that led us to focus on NR2F6 among >40 candidate NRs." (PMID 37406115, 2023). "We then inoculated C57BL/6 mice with cells from NR1H3 or NR3C1 OE, NR2F6 KD, or control wild-type (WT) B16F10 melanoma lines; treated animals with anti–PD-1 antibodies; and evaluated them for responses to ICT." (PMID 37406115, 2023). "Notably, CD8+ T cell depletion did not fully rescue the growth of NR2F6 KO tumors to the degree seen in control NR2F6 WT tumors, suggesting that increased antitumor immunity seen in NR2F6-deficient melanoma is predominantly, but not solely, mediated by tumor-infiltrating CD8+ T cells." (PMID 37406115, 2023). "To further assess candidate NR2F6 effectors, we first validated NACC1, FKBP10, and CXCL10 expression levels in NR2F6 KD or KO mouse melanoma cells." (PMID 37406115, 2023). "In agreement, NR2F6 expression did not correlate with FKBP10 expression in melanoma cells [quantitative reverse transcription polymerase chain reaction (qRT-PCR) and cancer cell line encyclopedia (CCLE)]." (PMID 37406115, 2023). "Inhibition of NR2F6 expression by either shRNA KD or CRISPR-mediated KO inhibited melanoma growth in immune-competent but not immune-incompetent mice, an outcome phenocopied by NACC1 and FKBP10 loss." (PMID 37406115, 2023). "Notably, patients whose melanoma specimens showed high NACC1 and FKBP10 expression exhibited the worst overall survival, and those specimens also exhibited the highest NR2F6 expression relative to specimens expressing low NACC1 and FKBP10." (PMID 37406115, 2023). "Among NRs expressed in >10% of melanoma cells were NR1H3, NR3C1, NR2F6, and ESRRA." (PMID 37406115, 2023). "Furthermore, NR2F6 inhibition has been shown to augment the efficacy of ICB in preclinical prostate, melanoma, and colorectal cancer models, as well as increase tumor infiltration by IFNγ-positive T cells." (PMID 32117236, 2020). "Notably, analysis of melanoma patient data provided important support for our findings, revealing higher expression of NR2F6/NACC1/FKBP10 in nonresponders to ICT." (PMID 37406115, 2023).
leukemia (7 papers, 2016 to 2025). A malignant (clonal) hematologic disorder, involving hematopoietic stem cells and characterized by the presence of primitive or atypical myeloid or lymphoid cells in the bone marrow and the blood. "In leukemia, NR2F6 increases long-term hematopoietic stem cells (LT-HSC) and prevents proliferative arrest associated with terminal differentiation." (PMID 34073258, 2021). "Finally, an effect on cancer stem cells is possible as it is known for leukemia that NR2F6 increases long-term hematopoietic stem cells, while a blockade initiates terminal differentiation." (PMID 34073258, 2021). "It has been suggested that miR-130b regulates growth arrest in B-lymphoid differentiation, and these mechanisms contribute to the direct downregulation of tumor suppressor genes NR2F6 and SGMS1 in MLL-rearranged leukemia." (PMID 36278683, 2022). "NR2F6 is a prospective biomarker, for tumor cells and long-term hematopoietic stem cells (LT-HSC) proliferation, metastasis, survival ability plays an important role, and can inhibit the differentiation process of leukemia cells." (PMID 40424451, 2025).
colitis (4 papers, 2018 to 2025). Inflammation of the colon. "Nr2f6-deficient mice are highly susceptible to DSS-induced colitis; mechanistically, NR2F6 directly binds to a consensus sequence at −2 kb of murine and human MUC2 promoter and transactivates Muc2 expression." (PMID 31139192, 2019). "Loss of NR2F6, therefore, increases intestinal permeability and results in spontaneous late-onset colitis in Nr2f6-deficient mice." (PMID 31139192, 2019). "In parallel to the major constituent of the mucus layer Muc2, the multidrug resistance 1 (MDR1) and NEMO which have been established to be important for epithelial barrier function, loss of NR2F6 led to spontaneous colitis development in aged mice." (PMID 28779026, 2018). "During DSS colitis, Muc2 and Muc3 expression was selectively reduced in Nr2f6-deficient colonic scrapings whereas Muc1, Muc4 and Muc5ac expression was unaltered." (PMID 28779026, 2018). "As reduced Muc1 expression protects mice from DSS-induced colitis, this observation cannot be causative for the enhanced colitis sensitivity in the Nr2f6-deficient setting." (PMID 28779026, 2018). "We found Nr2f6−/− and wild-type BM-reconstituted Nr2f6−/− mice to be highly susceptible to DSS-induced colitis, whereas Nr2f6−/− BM-reconstituted wild-type and wild-type mice showed a less severe phenotype." (PMID 28779026, 2018). "Loss of NR2F6 alters intestinal permeability and results in spontaneous late-onset colitis in Nr2f6-deficient mice." (PMID 28779026, 2018). "Nr2f6-deficient mice were highly susceptible to DSS-induced colitis characterised by enhanced weight loss, increased colonic tissue destruction and immune cell infiltration together with enhanced intestinal permeability and reduced Muc2 expression." (PMID 28779026, 2018). "T cell transfer colitis and bone marrow reconstitution experiments demonstrated that disease susceptibility was not dependent on the expression of Nr2f6 in the immune compartment but on the protective role of NR2F6 in the intestinal epithelium." (PMID 28779026, 2018). "In order to determine whether enhanced inflammation and tissue destruction of the epithelial barrier during DSS colitis is causative of enhanced activation-dependent potential of Nr2f6−/− CD4+ (CD25−CD62LhiCD44lo) T cells, we used a model of T cell-dependent colitis." (PMID 28779026, 2018). "Loss of NR2F6 resulted in reduced intestinal barrier function, increased susceptibility to dextran sodium sulfate (DSS) induced colitis and spontaneous late-onset colitis." (PMID 36052079, 2022). "In order to investigate the role of NR2F6 in experimental colitis disease progression, we administered 3.5% DSS in the drinking water to wild-type as well as Nr2f6-deficient mice." (PMID 28779026, 2018).
liver cancer (4 papers, 2021 to 2024). An epithelial or non-epithelial malignant neoplasm that arises from the liver. "For example, circRHOT1 induces liver cancer development by recruiting TIP60 (also known as histone acetyltransferase KAT5) to the promoter of nuclear receptor subfamily 2 group F member 6 (NR2F6), thereby inducing NR2F6 expression." (PMID 38697964, 2024). "Moreover, it has been found that circRHOT1 contributes to the malignant progression of liver cancer by inhibiting NR2F6 expression." (PMID 33686957, 2021).